GATA3 (GATA binding protein 3)
Diseases named in the same sentence as GATA3 in open-access papers (continued):
Sharing a sentence is not in itself a finding about the gene and the disease.
deafness (22 papers, 2009 to 2025). An inherited or acquired condition characterized by the complete loss of the ability to hear from one or both ears. "This is the first study reporting only deafness and renal abnormalities as symptoms of the p.Arg367* mutation in the GATA3 gene, and also the sixth HDR syndrome case in the world, and the first on the American continent." (PMID 30534854, 2018). "Patients with GATA3 deletion have a higher incidence of profound deafness (p < .05), and this can be interpreted by the deletion of other involved genes." (PMID 32155322, 2020). "An additional study discovered a haploinsufficiency on 10p13-10p14, a more proximal region on GATA3, that presented with DiGeorge-like features and bilateral deafness, but without other HDRS characteristics." (PMID 41019281, 2025).
triple-negative breast carcinoma (22 papers, 2013 to 2025). An invasive breast carcinoma which is negative for expression of estrogen receptor (ER), progesterone receptor (PR), and human epidermal growth factor receptor 2 (HER2). "Limited studies have investigated the diagnostic value of this gene in triple-negative breast cancer and compared its diagnostic value with GATA-3, and this issue requires more detailed and extensive studies." (PMID 37383162, 2023). "Regarding the limitation of previous studies in the field of introducing new diagnostic markers for the diagnosis of triple-negative breast cancer, in this study, the diagnostic value of GATA-3 and GCDFP-15 markers was investigated." (PMID 37383162, 2023). "GATA-3 and GCDFP-15 may serve as diagnostic markers for triple-negative breast cancers and GATA-3 seems to be more reliable." (PMID 37383162, 2023). "Studies have shown that the positive rate of TRPS1 in ER-positive breast cancer is 98%, similar to GATA3 (96%), while the positive rate in triple-negative breast cancer (TNBC) is 86%, significantly higher than GATA3 (45%)." (PMID 40822238, 2025). "SOX10 is a fairly sensitive marker for triple-negative breast cancer but it should always be used in conjunction with GATA3 immunohistochemical stain." (PMID 38813332, 2024). "GATA-3, also strongly positive in this carcinoma, is positive in 91-100% of hormone receptor-positive breast cancers, and 43-66% in triple-negative breast cancers." (PMID 39022491, 2024). "In women with well-differentiated luminal A tumors, GATA-3 expression is high, while its lower expression is reported in triple-negative breast carcinomas, which are more aggressive." (PMID 37483298, 2023). "The aim of this study was to investigate the expression level of GCDFP15 and GATA3 in triple-negative breast cancer." (PMID 37383162, 2023). "In triple-negative breast cancer cells, melatonin induces kisspeptin expression by increasing the expression and transcriptional activation of GATA3." (PMID 35101033, 2022). "In agreement with its function as a determinant of breast epithelium luminal differentiation, we observed low levels of GATA3 levels in triple-negative breast cancer cases, a majority of which are likely to correspond to basal-like phenotypes." (PMID 24205108, 2013). "Our lab and others have shown that overexpression of GATA3 in the metastatic MDA-MB-231 (MB-231) basal triple-negative breast cancer cell line reduces tumorigenesis and metastasis." (PMID 23577196, 2013). "Additionally, SOX, which was predicted to change the motif factor binding site by MYLK, was suggested to sensitive triple-negative breast cancer marker along with GATA-3." (PMID 33800915, 2021). "Moreover, comparison of the expression of UTX, Vimentin, and GATA transcription factor family in normal and triple-negative breast cancer samples using the TCGA database also show marked downregulation of GATA3 and UTX, whereas GATA6 was significantly upregulated." (PMID 31685800, 2019). "EZH2 inhibitors remove this repressive mark, opening GATA3 enhancers, upregulating GATA3 expression, and synergizing with AKT inhibitors to induce differentiation and apoptosis in triple-negative breast cancer (TNBC) cells." (PMID 40032852, 2025). "In this study, we decided to investigate the expression of GATA3 and GCDFP15 genes in triple-negative breast cancers." (PMID 37383162, 2023). "The distribution of immunopositive reactions in atypical cells of triple-negative breast cancer among patients, depending on the marker, was as follows: NIS-positive reactions were found in 112 women (69.5%); Mammaglobin in 50 (31.0%); and GATA-3 in 102 (63.3%)." (PMID 41283251, 2025). "In this study, we evaluated the expression of GATA3 and GCDFP15 in triple-negative breast cancers." (PMID 37383162, 2023). "GATA-3 and GCDFP-15 may be two markers for the diagnosis of triple-negative breast cancers with different prevalences." (PMID 37383162, 2023).
eosinophilia (20 papers, 2008 to 2025). "OVA-mRNA-LNP–treated mice displayed reduced airway resistance, decreased eosinophilia, diminished proportion of Th2 (GATA3+) cells, and increased IFN-γ+ CD4+ T cell frequency, paralleling the acute response." (PMID 40985871, 2025). "Following challenge with np-Der p1 protein, immunized mice exhibited reduced allergic responses, including lessened eosinophilia, decreased Th2 (GATA3+ and IL-5+IL-13+) and Th17 (IL-17A+) cell frequencies, and lowered mucus production." (PMID 40985871, 2025). "Similar to the temporal pattern of eosinophilia, GATA3+ TH2 cells and ILC2 numbers tended to increase between 3 and 7 dpi, and both cell types were decreased in response to DP2 antagonism or DP1 agonism." (PMID 39592603, 2024). "IL-4 stimulates the activation of GATA-3, which is a Th2 cell transcription factor, through a positive feedback loop, leading to the secretion of IgE by activating B cells, inducing eosinophilia, and stimulating airway hyperreactivity." (PMID 37569846, 2023). "Nonetheless, the observed increase in Gata3+ Th2 cells is consistent with the increased eosinophilia we had observed in mice that underwent neutrophil depletion during allergic sensitization." (PMID 35191395, 2022). "GMP administration significantly decreased IL-5, IL-13 and GATA3 expression in the intestinal tissue of FA animals, which is in accordance with reduced eosinophilia, goblet cell hyperplasia and IgE gene expression in small intestine of GMP treated rats." (PMID 32992996, 2020). "The results of our randomized clinical trial in COPD patients with sputum eosinophilia demonstrate that a Th2-regulated airway inflammation can be effectively attenuated by inhalation of the GATA3-specific DNAzyme SB010." (PMID 29615049, 2018). "We could demonstrate that it is feasible to reduce sputum eosinophilia in the sputum eosinophil-high subgroups of COPD patients inhaling the GATA3-specific DNAzyme SB010 over a period of 4 weeks." (PMID 29615049, 2018). "Also, on sole HDM exposure, reduced eosinophilia and goblet cell metaplasia were observed in the Gata-3+/nlslacZ mice in comparison with their littermates." (PMID 27315767, 2017). "Interestingly, expression of GATA-3, CCR3, -4, -8, and ST2L, and the generation of blood eosinophilia, is intact in mice doubly deficient in both IL-4 and IL-13." (PMID 18315837, 2008). "Abolished GATA3, IRF4, and BATF expression in Stim1/2-deficient Tregs may thus explain the type 2 autoimmunity in Stim1/2Foxp3 mice, which is characterized by elevated Th2 cytokines, increased IgE levels and eosinophilia." (PMID 30862784, 2019). "This also reduced their expression of Gata3, Il4, Il5, and Il13 in lung conventional CD4+ T cells: these effects markedly reduced the eosinophilia and AHR." (PMID 37917548, 2023). "Neither Th2 cytokines nor the transcription factor GATA3 as well as features triggered by IL-4 (IgG1 antibodies, RELM-ß) or IL-5 (eosinophilia) could be detected in co-infected animals." (PMID 28791259, 2017).
renal dysplasia (20 papers, 2010 to 2025). Renal dysplasia is a form of renal malformation in which the kidney(s) are present but their development is abnormal and incomplete. "Renal dysplasia has been linked to GATA3 insufficiency as well, revealing the substantial role of GATA3 in renal cell development." (PMID 39768217, 2024). "GATA3 is strongly expressed in two major progenitor populations, ureteric bud and stroma cells, and plays a crucial role in kidney development which explains the occurrence of renal dysplasia." (PMID 38116790, 2023). "Our case carried a de novo variant in causative gene, GATA3, but presenting no renal dysplasia or family history." (PMID 33363791, 2020).
colorectal cancer (19 papers, 2014 to 2025). A primary or metastatic malignant neoplasm that affects the colon or rectum. "Research revealed that GATA3 is low-expressed in colorectal cancer, and its low expression is associated with high histological malignancy grade, lymph node metastasis, and poor prognosis of CRC." (PMID 32760217, 2020). "GATA3 is up-regulated in ulcerative colitis, which is associated with increased risk of colorectal cancer." (PMID 24743840, 2014). "Further study of the role of variants in GATA3 in colorectal cancer will yield more insight into their functional significance." (PMID 24743840, 2014). "Our results provide strong evidence for a gene-diet interaction and colorectal cancer risk between a genetic variant (rs4143094) on chromosome 10p14 near the gene GATA3 and processed meat consumption (p = 8.7E-09)." (PMID 24743840, 2014). "The rs1269486 variant is located 1420 bases upstream of GATA3 in a region of open chromatin (DNase I hypersensitivity) with histone methylation patterns consistent with promoter activity in a colorectal cancer cell line (CACO2)." (PMID 24743840, 2014). "A recent genome-wide analysis identified an interaction between a SNP on chromosome 10p14 near the GATA3 gene and processed meat that modified colorectal cancer risk, suggesting that GATA3 transcription triggers a pro-tumorigenic inflammatory response to processed meat." (PMID 28956832, 2017). "Nonetheless, the precise mechanism by which deregulation of GATA3 is linked to colorectal cancer upon consumption of high levels of processed meat remains unclear." (PMID 24743840, 2014). "Among previously not reported associations with overall survival were mutations in GATA3 and FANCE genes in colorectal cancer, mutations in gene PTPN11 in glioma, and mutations in RNF43, MSH6 and FBXW7 genes in endometrial cancer." (PMID 39277826, 2024). "GATA3 staining can be used to distinguish primary EMPD from pagetoid melanoma in situ and secondary EMPD caused by colorectal carcinoma." (PMID 28693610, 2017). "Some cancers showed GATA3 overexpression, such as breast and colorectal carcinoma." (PMID 37629741, 2023). "MiR-195-5p was reported to inhibit NOTCH2 expression and activation in a post-transcriptional manner, leading to the down-regulation of NOTCH2/GATA3-mediated IL-4 secretion in colorectal cancer cells, ultimately suppressing M2-like TAM polarization and tumor progression." (PMID 35996149, 2022). "Besides, the influence of GATA3/miR-29b axis on colorectal cancer cells to Oxaliplatin should be further confirmed in a xenograft assay." (PMID 32760217, 2020). "For example, in colorectal cancer, NOTCH2 expression was shown to enhance GATA3-mediated IL-4 secretion, directly promoting M2-type TAM polarization." (PMID 41200204, 2025). "SETD2 sustains GATA3 expression in human Treg cells, and SETD2 expression is increased in Treg cells from human colorectal cancer tissues." (PMID 36463230, 2022). "GATA binding protein 3 (GATA3) and miR-29b are related to colorectal cancer (CRC)." (PMID 32760217, 2020). "Interestingly, we observed that increased SETD2 expression was accompanied by enhanced GATA3 expression in Treg cells in cancerous tissues from colorectal cancer (CRC) patients compared with noncancerous colorectal tissues." (PMID 36463230, 2022).
COVID-19 (19 papers, 2020 to 2025). A disease caused by infection with severe acute respiratory syndrome coronavirus 2. "The prevalence of COVID-19 is increasing worldwide, and GATA3-mediated Th1 cells are the main fighters during the disease progression." (PMID 39768217, 2024). "The previous report reinforced the severity and fatal outcomes of COVID-19 to remarkable elevations in GATA3, RORγt, and T-bet, while sharp reductions in FoxP3 expression levels were recorded." (PMID 39768217, 2024). "Further work is required to provide a deeper insight into the role of GATA3 in the pathophysiology of COVID-19 and how it may apply to improve therapeutic approaches." (PMID 39768217, 2024). "We then studied TFs potentially involved in the transcriptomic changes observed in COVID-19 monocytes, using Discriminant Regulon Expression Analysis (DoRothEA), and found that MAF family members, GATA3, STAT4, and IRF4, were associated with upregulated genes in severe COVID-19." (PMID 36443794, 2022). "Hence, GATA3 might be involved in COVID-19 dysregulated mechanisms due to the abnormal T-cell responses." (PMID 39768217, 2024). "The RS between activation marker concentrations and the severity of COVID-19 are calculated by training data set Z2KP, where the activation markers are IL-17a, IL-2, GATA3, IFN-γ, IL-4, IL-10, PD_1, CD40L, RORγt, CTLA_4, CCR7, TNF-α and IL-6, respectively." (PMID 36845115, 2023). "Severe COVID-19 patients that develop lung injury showed expanded KLRG1+ Tregs that express Cxcr3, Il10, Il12b1, Ilrb1, Tbx21, Gata3 gene signatures similar to what was found in this study." (PMID 35634302, 2022). "Among CD4+ T cells, there was a predominant Th2 and Th17 response with increased gene expression of GATA3 and RORG transcription factors, more prominent in severe COVID-19 and SARS-CoV-2 antibody-producing patients." (PMID 35962159, 2022). "To highlight, S. salivarus, which is increased in severe COVID-19 patients, seems to reduce colonic α- diversity and decrease T helper (Th) cells related cytokines or transcription factors, namely IFN-γ (Th1), GATA-3 (Th2) and TGF-β (Treg) in mouse pups." (PMID 36483197, 2022). "Similar percentages of CD4+ T cells expressing CCR4, CCR6, CD161, CXCR3, TBET, and GATA3 were found among healthy donors and pregnant women with or without COVID-19." (PMID 34326336, 2021). "Notably, in our RNA-Seq data set, Stat6 and Gata3 were not upregulated during COVID-19 in mice, which may reflect an inability to detect changes in these mRNAs at that time point." (PMID 34185704, 2021). "Despite COVID-19 individuals having a discreet increase in the frequency of CD4+T-bet+ T cells following spike stimulation, compared to HD, the GATA3/T-bet ratio was not modified." (PMID 40458413, 2025).
metastatic tumors (19 papers, 2014 to 2025). "Strong associations emerged between mutations in ESR1, GATA3, and PIK3CA in metastatic tumors, particularly ESR1 mutations at positions 380, 536, 537, and 538 pairing with PIK3CA mutations at positions 542, 545, and 1047." (PMID 40758706, 2025). "We further examined the expression of GATA3 in 10 matched primary-metastatic tumor samples from head and neck cancer patients, and the level of GATA3 was higher in the metastatic tumors." (PMID 30218063, 2018). "In the 4T1 orthotopic model, the expression of Gata3 in the metastatic tumors was significantly higher than that in the primary tumor." (PMID 30218063, 2018). "GATA3 has been well-studied and is used to assist in diagnosing metastatic tumors of breast origin." (PMID 40822238, 2025). "GATA3 serves as a powerful diagnostic marker for BC, outperforming traditional markers like gross cystic disease fluid protein 15 (GCDFP-15) and mammaglobin due to its stronger positivity and consistency in both primary and metastatic tumors." (PMID 39768217, 2024). "Here, we found that metastatic tumors express higher levels of GATA3 compared with primary tumors." (PMID 30218063, 2018). "The expression of GATA3, a transcription factor responsible for promotion of the differentiation of Th2 cells and the inhibition of Th1 development, was found to be increased in the benign tumors in comparison to healthy tissue as well as malignant and metastatic neoplasms." (PMID 32225066, 2020). "In cases of EBC, IHC markers such as GATA3, mammaglobin, and GCDFP-15 play a critical role in confirming mammary origin and distinguishing these tumors from adnexal or metastatic neoplasms." (PMID 40895939, 2025). "Among them, GATA-3 (GATA binding protein 3), GCDFP-15 (gross cystic disease fluid protein 15), and mammaglobin are most commonly used for the detection of primary and metastatic disease." (PMID 36120242, 2022). "Additional immunostaining on the metastatic tumor was positive for GATA3, androgen receptor and estrogen receptor, but negative for progesterone receptor." (PMID 38831459, 2024). "Interestingly, GATA3 has proved useful in differentiating between primary and metastatic tumours in patients with a history of BC regardless of molecular subtype." (PMID 37345165, 2023). "GATA3, TTF-1, S100, p40, PAX8, p63, NKX3.1, CDX2, SALL4, CD30 (-) were detected to rule out metastatic disease." (PMID 40978995, 2025).